TLR3 (toll like receptor 3)
Diseases named in the same sentence as TLR3 in open-access papers (continued):
Sharing a sentence is not in itself a finding about the gene and the disease.
viral infection (continued). "Our results reveal that TRIF-dependent RIP-1 and TRAFs activation by TLR3 is critical for IL-32-mediated pro-inflammatory cytokines production in ocular mucous surfaces after viral infection." (PMID 25754842, 2015). "Other virus infection models have demonstrated that TLR3 stimulation in dendritic cells decreases production of nitric oxide which in turn increases proteasomal activity and consequently increases viral antigen processing and presentation." (PMID 25452586, 2015). "TLR-3 is known to play a key role in the host response to virus infection by detecting virus-derived dsRNA in intracellular vesicles, whereas TLR-2 and TLR-4 recognise viral structural proteins on the plasma membrane." (PMID 25973612, 2015). "Established BFCE-K4DT cells are expressing TLR3, thus this cells are suitable for the study accompanied with not only bacterial infection but also viral infection." (PMID 26624883, 2015). "Further, we show that conditioned media from bronchial epithelial cells as well as RV infection and stimulation with viral infection mimics acting on TLR3 and RIG-I-like receptors increase IL-33 in BSMCs from both healthy and asthmatic individuals." (PMID 26318341, 2015). "Because TLR3-mediated mast cell activation is required for the recruitment of CD8+ T cells to the site of viral infection in some situations, TLR3-mediated systems provide different contributions depending on the type of virus and on the route of infection." (PMID 25550087, 2015). "TLR3 is a well-defined receptor for viral RNA, which can induce NF-κB activation during viral infection." (PMID 26199460, 2015). "TLR3 immunity appears to be a potent threat to viral infections and plays critical roles in protection against virus encephalitis (such as HSV and the West Nile virus)." (PMID 25938551, 2015). "Viral infections or TLR (e.g. TLR3) engagement activates IRF7, which initially participates in the transcriptional induction of small amounts of type I IFNs." (PMID 25978633, 2015). "Consistent with the mRNA results, increased expression of MDA5, RIG-I and OAS2 was observed and TLR3 expression was less robust at the protein level upon virus infection." (PMID 25550087, 2015). "By virus infection, activations of some certain PRRs such as TLR3, RIG-I and MDA5 result in the phosphorylation and nuclear translocation of IRF3 and IRF7." (PMID 25759845, 2015). "TLR3-mediated immunity to natural infection in humans has been demonstrated to both limit and exacerbate viral disease progression." (PMID 25452586, 2015). "It is well known that TLR3 recognizes ds-RNA during viral infection to induce type-I interferon synthesis in a variety of different cell types." (PMID 25798928, 2015). "Currently, the relationships between miR-155 and TLR3 have been extensively studied in virus infection, immune response and tumour formation." (PMID 25938551, 2015). "When viral infection occurs, TLR3 in endosomes and RIG-I, MDA5, and LGP2 in the cytoplasm recognize the dsRNA." (PMID 26659307, 2015). "RIG-I-MAVS and TLR3 molecular pathways following viral infection: As RNA virions enter the cells, they lose the envelope and become internalized, which is followed by release of its genome." (PMID 24710104, 2014). "In viral infection, four TLRs, including TLR3, TLR7, TLR8 and TLR9, seem to play critical roles in the recognition of viral nucleic acid components, and TLR2 and TLR4 were shown to detect viral components such as envelope glycoproteins." (PMID 25188232, 2014). "TLR3 is a key sensor of viral infection, as most viruses will produce dsRNA at some stage of its life cycle." (PMID 25369126, 2014). "By using an experimental model in which a specific molecular pathway is activated, we would be able to demonstrate that TLR3 signaling is one of the components of an immunological reaction during viral infections in the olfactory mucosa." (PMID 24744264, 2014).
viral infection (continued). "Toll-like receptor 3 (TLR3) is a key component of the innate immune system and has the ability to detect virus infection and trigger host defence responses." (PMID 25057274, 2014). "Conflicting reports on the role of TLR3 pathway in viral infection in humans and mice have been documented." (PMID 25393122, 2014). "Correspondingly many virus infections are sensed by TLR3, including RSV (parainfluenza virus), rhinovirus (picornavirus), reovirus (reovirus), Epstein Barr Virus (EBV), and HSV-2 (both herpes viruses)." (PMID 23435233, 2013). "The transcript level of IL-33 was highly increased in L2-MHV3 induced hepatitis than Poly(I:C) treated mice demonstrating a difference between TLR-3 agonist and natural virus infection in liver." (PMID 24058536, 2013). "TLR3 plays a direct role in recognition of virus infection, evidenced by the finding that genomic dsRNA from reovirus activates cytokine production." (PMID 23435233, 2013). "TLR3, TLR7 and TLR8 have been implicated in responses to virus infection in animal models, TLR3 through recognition of dsRNA and TLR7 and TLR8 through recognition of ssRNA and small nucleoside analogues." (PMID 23824215, 2013). "Poly(I:C) is a synthetic mimic of viral dsRNA and induces immune responses similar to those seen during viral infection through the activation of TLR3." (PMID 23405061, 2013). "It has been shown that viral infections trigger the activation of innate immune pathways and type I interferon response via TLR3." (PMID 23882263, 2013). "As with the double stranded RNA generated during a viral infection, this synthetic RNA is detected by the immune system as being foreign by the transmembrane protein toll-like receptor 3 TLR-3)." (PMID 24409130, 2013). "These in vivo studies indicated that, after viral infection, the levels of TLR3-4 and especially TLR7-8 were increased in the lungs." (PMID 24039959, 2013). "Toll-like receptor 3 is an endosomal PRR that senses dsRNA typically produced during viral infection." (PMID 24302927, 2013). "This raises the possibility that use of Aspirin as an anti-inflammatory molecule during TLR-3 simulated viral infection is ineffective." (PMID 23398903, 2013). "TLR3 plays a major role in the recognition of virus infection leading to the induction of the IFN pathway." (PMID 23316105, 2012). "Pregnant rats were treated with the double-stranded RNA polyinosinic:polycytidylic acid (poly(I:C); 10 mg/kg) which mimics immune activation occurring after activation of Toll-like receptors-3 (TLR3) by viral infection." (PMID 22681877, 2012). "The mRNA expression of RIG-I, MDA5, and TLR3 was markedly upregulated directly by viral infection and also by treatment of uninfected cells with virus-free supernatant." (PMID 23185463, 2012). "On the other hand, a detrimental effect of Tlr3 signaling on the outcome after viral infection was noted in several animal models." (PMID 22570612, 2012). "TLR-3 in biliary epithelial cells protects against viral infections by secretion of IFN-gamma, inducing apoptosis of infected hepatocytes, as reported in biliary atresia." (PMID 22114589, 2011). "Activation of TLR3 with poly IC prior to viral infection also exacerbated disease development, whereas such activation after viral infection slowed disease development." (PMID 22189096, 2011). "In contrast, it has also been reported that the presence of TLR3 provides protection from acute viral infections with West Nile virus and Coxsackievirus B4." (PMID 22189096, 2011). "Activation of TLR3 signaling prior to viral infection hindered the induction of protective IFN-γ-producing CD4+ and CD8+ T cell populations." (PMID 22189096, 2011). "Traditionally, TLR3 is known to recognize double-stranded RNA and double-stranded mRNA, following viral infection." (PMID 21342497, 2011). "Another common pathway upstream of IRF3 activation is the engagement of TLR3 by viral dsRNA, which is produced as a replication intermediate during viral infection." (PMID 21436888, 2011).
viral infection (continued). "On the other hand, other studies have suggested that TLR3 plays a detrimental role upon viral infection." (PMID 21637773, 2011). "On the other hand, further activation of TLR3 signaling after viral infection appears to enhance anti-viral T cell function by reducing the expression of inhibitory PDL-1 and preventing the generation of regulatory T cells." (PMID 22189096, 2011). "It is possible that, while addition of LL37 protein enhances TLR3 signaling in our studies, other, as yet unidentified endogenous factor(s) enhance viral sensing by TLR3 during viral infection." (PMID 22039520, 2011). "Activation of TLR3 signaling prior to viral infection hindered the induction of protective IFN-γ-producing CD4+ and CD8+ T cell populations, but elevated PDL-1 expression and regulatory CD4+ T cell generation in the CNS." (PMID 22189096, 2011). "The innate immune responses to virus infection are initiated by either Toll-like receptors (TLR3/7/8/9) or cytoplasmic double-stranded RNA (dsRNA)-recognizing RNA helicases RIG-I and MDA5." (PMID 21695056, 2011). "The finding that poly I:C, an activator of TLR3 and RNA helicase signaling also induced Lcn2 gene expression in the C8 microglia indicates that additional innate signaling pathways associated with viral infection may also regulate the expression of the Lcn2 gene." (PMID 21943033, 2011). "Polyinosinic:polycytidylic acid (poly I:C) is a toll-like receptor-3 (TLR3) agonist and induces type I interferons, thus mimicking inflammatory responses to systemic viral infection." (PMID 20399848, 2010). "In this review, we summarize the recent findings regarding the role of TLR3 in liver injury, inflammation, regeneration, fibrosis, viral infection, and autoimmune liver disease." (PMID 20936107, 2010). "Relocation of TLR3 during viral infection has only previously been described for respiratory syncitial virus (RSV)." (PMID 19247444, 2009). "High levels of TLR3 are found in glial cells and neurons in disorders of the brain, neurodegenerative diseases and viral infections." (PMID 19247444, 2009). "The TLR3 pathway plays a role in the clearance of certain virus infections and survival of the infected organism." (PMID 19025601, 2008). "In particular, infections with Punta Toro virus (PTV), influenza A, and vaccinia all led to significant increases in interleukin-6 (IL-6) in WT mice both systemically and at the infected tissues, suggesting the cytokine as a key regulator of TLR3-induced pathogenesis in viral infections." (PMID 39988665, 2025). "Poly I:C, a synthetic analogue of dsRNA, mimics viral infection and activates TLR3." (PMID 41255761, 2025). "We also demonstrated that PBE cells possess a functional TLR3 suggesting that this cell line could be a useful in vitro tool to study viral infections that affect the porcine respiratory epithelium." (PMID 40565228, 2025). "To mimic viral infection, we used poly(I:C), which can activate innate immunity via TLR3." (PMID 40937152, 2025). "The duality of TLR3 seen in cancer is also evident in the pathogenesis of infectious diseases, as evidence suggest that the dsRNA sensing capabilities of TLR3 can either attenuate or exacerbate symptoms of viral infection." (PMID 39988665, 2025). "TLR3 senses viral dsRNA to initial host immune responses against viral infections." (PMID 40495154, 2025). "TLR3 detects double-stranded RNA (dsRNA) from viral infections." (PMID 41488646, 2025). "TLR3 is key to antiviral immunity, and TLR3 agonists can protect against viral infections." (PMID 40102400, 2025). "Alteration in TLR3 transcriptional activity may influence receptor functionality and the development of viral diseases." (PMID 40831704, 2025). "The TLR3 rs5743305 T/A and TLR3 rs3775291 C/T polymorphisms were selected for this study because they had not yet been evaluated in HTLV-1 infection, although they were associated with other viral infections." (PMID 40831704, 2025).
viral infection (continued). "The innate immune system constitutes the primary defense against viral infections, employing pattern recognition receptors (PRRs), including Toll-like receptor 3 (TLR3), RIG-I-like receptors (RLRs), and cyclic GMP-AMP synthase (cGAS) to recognize viral elements and activate antiviral responses." (PMID 40264759, 2025). "Thus, it would be interesting to investigate the effect of extracellular GzmK on PAR-1 and TLR3 cooperative action during viral infections." (PMID 41009359, 2025). "Several studies have demonstrated the role of TLR3 in the pathophysiology of cervical cancer, as it plays a critical role in detecting viral infections, such as HPV, and its activation may contribute to a deregulated immune response." (PMID 39208235, 2024). "This study investigates the role of interferon‐stimulated gene 56 (ISG56), one of the ISGs that suppress viral replication, downstream of Toll‐like receptor 3 (TLR3), a receptor that recognizes viral infection, in cultured human proximal tubular epithelial cells (hRPTECs)." (PMID 38923445, 2024). "In liver viral infection, TLR3/TRIF-mediated signaling acts as a double-edged sword." (PMID 38694821, 2024). "Furthermore, the importance of TLRs in viral infections has been underscored by the finding that TLR3, TLR7, and TLR8, along with cytoplasmic RIG-I-like receptors, facilitate the initiation of innate immune responses by recognizing viral nucleic acids." (PMID 38732254, 2024). "TLR3 is an endosomal sensor of double-stranded RNAs, which may be intermediates or by-products of viral infections." (PMID 39048830, 2024). "Nonetheless, TLR3 or related pathogen recognition receptors might provide a link between viral infection/replication and sentinel cell activation." (PMID 39052353, 2024). "The significance of TLRs in viral infections is further highlighted by reports that TLR3, TLR7, and TLR8, along with cytoplasmic retinoic acid-inducible gene I (RIG-I)-like receptors, are instrumental in initiating innate immune responses against viral nucleic acids." (PMID 38732254, 2024). "Structurally similar to double stranded RNA, polyinosinic-polycytidylic acid (poly (I:C)) can activate the Toll like receptor 3 (TLR3) pathway to mimic viral infection and induce the subsequent NF-κB activation and cytokines production, leading to pulmonary inflammation and dysfunction 18,19." (PMID 38164360, 2024). "Among the TLRs, TLR3 plays a protective role against viral infections." (PMID 38203397, 2023). "All articles on this TLR3 SNP included in the meta-analysis were on viral infections." (PMID 37510216, 2023). "In vivo data collected from early life studies may suggest that neuronal TLR3 stimulation is detrimental in neurodegenerative disease, especially in the context of viral infections including Epstein-Barr virus and hepatitis C." (PMID 35639336, 2023). "However, the molecular mechanism by which TLR3 functions in the viral infection response in teleosts remains to be investigated." (PMID 36670828, 2023). "Polyinosinic-polycytidylic acid (Poly I:C), an dsRNA analog, can activate innate immunity to a viral infection via toll-like receptor 3 (TLR3) which could be beneficial to the action of sub-unit vaccine." (PMID 37450510, 2023). "However, the relationship between TLR3 activation by viral infection and mtROS generation remains largely unexplored." (PMID 38203397, 2023). "Intracellular reactive oxygen species (ROS) are involved in TLR3-induced inflammatory responses during viral infections; however, their relationship with mitochondrial ROS (mtROS) remains largely unknown." (PMID 38203397, 2023). "Since TLR3 can recognize the double-stranded RNA (dsRNA) structure produced by viral infections." (PMID 37002312, 2023). "In addition, an upregulation of chicken TLR3 in spleen at 24 h after a virus infection was determined in a previous report, which is consistent with our present results in yellow catfish." (PMID 36670828, 2023).
viral infection (continued). "It first declined and then increased to a peak at 24 h followed by declining after poly (I:C) challenge for 48 h, indicating that TLR3 may regulate the immune response triggered by dsRNA virus infections in spleen and kidney." (PMID 36670828, 2023). "TLR3 also detects viral infection and initiates an innate immune signalling pathway." (PMID 36679906, 2022). "Thus, RLR, TLR3, and NEMO deficiency all lead to susceptibility to viral infection and serious sequelae, such as herpes simplex virus type 1 encephalitis." (PMID 35289316, 2022). "To determine whether maternal- and fetal-derived cells respond differently to viral infections, we compared the transcriptional profiles and immunological secretomes from organoids treated with a ligand to stimulate toll-like receptor 3 (TLR3) signaling." (PMID 35975985, 2022). "This may inactivate TLR3 signal during virus infection, resulting in reduced IRF-3 activation and type I IFN production, thus causing a recognition disorder of pathogenic microorganisms and inadequate immune response." (PMID 35462764, 2022). "Toll receptors might have a function in limiting the virus infection in vector and upregulation of TLR3 might be activated upon ChiLCV infection to preclude the adverse effect of the virus on the vector." (PMID 35572639, 2022). "TLR3 recognises viral double-stranded RNA, and previous reports have shown that cytokines and chemokines are produced in bronchial epithelial cells via TLR3 activation during viral infection." (PMID 36560620, 2022). "Due to the notion that TLR3 recognizes dsRNA, which can be found in some viral genomes and is produced during viral replication cycles, it constitutes a key component in the recognition and clearance of certain viral infections." (PMID 36498932, 2022). "Additionally, the up-regulation of TLR3 occurs during multiple virus infections such as Muscovy Duck Reovirus (MDRV), Duck Tembusu virus (DTMUV), and Zika virus (ZIKV)." (PMID 35531338, 2022). "Although the exact mechanism by which glomerular damage develops is still unknown, the presence of TLR-3 in mouse kidneys suggest the contribution of viral infections." (PMID 36233224, 2022). "Since SSRIs potently inhibit IL-6 production via TLR3, SSRIs may be effective as therapeutic agents against cytokine storms induced by viral infection." (PMID 35814203, 2022). "Indeed, older studies have observed that viral infections with RNA viruses, which can trigger TLR3 activation, also induce an IL-12-independent induction of Th1 CD4+ T cell and IgG2a responses." (PMID 35296089, 2022). "Our previous studies in mice models have demonstrated that alveolar macrophages play an important role in the ability of nasally administered L. rhamunosus CRL1505 to modulate the antiviral innate immune response triggered by TLR3 activation and to increase the resistance against viral infections." (PMID 36230948, 2022). "Furthermore, antiviral mechanisms stimulated by IFN-stimulated genes and the TLR3 cascade were positively regulated, indicating that Rex triggers part of the viral infection response in host cells." (PMID 35216000, 2022). "These products, which mimic viral infection, may then be sensed by endosomal TLR3, 7, 8 or 9, and/or by cytoplasmic PRRs, including RIG- I, MDA5, cGAS." (PMID 33668131, 2021). "TLR3 recognizes dsRNA and hence, is most often studied in context of viral infections." (PMID 34280250, 2021). "Our findings suggest that vitamin D3 attenuates TLR3 agonist-induced inflammatory and fibrotic responses in BSMCs and support the clinical relevance of vitamin D3 supplementation in patients with viral infections having chronic respiratory diseases, such as asthma and COPD." (PMID 34512638, 2021). "Thus, we evaluated the expression of IFN-I and IFN-III transcripts by human primary nasal epithelial cells (HNEpC) in response to poly(I:C), a TLR3 agonist that mimics a viral infection." (PMID 34858406, 2021).